CERS4 (ceramide synthase 4)
Description:
Ceramide synthase that catalyzes formation of ceramide from sphinganine and acyl-CoA substrates, with high selectivity toward long and very-long chains (C18:0-C22:0) as acyl donor.
Synonyms: LASS4; FLJ12089; Trh1
Tractability: Antibody: UniProt predicts a signal peptide or a membrane-spanning region. PROTAC: its protein half-life has been measured.
Target class: Enzyme; Transferase
Gene: Protein-coding gene on chromosome 19 (8,206,736 to 8,263,716, forward strand). Ensembl gene ENSG00000090661.
Subcellular location: Endoplasmic reticulum membrane
Subcellular location (Human Protein Atlas): Nucleoplasm; Vesicles
Pathways (Reactome):
Metabolism: Sphingolipid de novo biosynthesis
Gene Ontology:
Molecular function: protein binding; sphingosine N-acyltransferase activity; DNA binding
Biological process: ceramide biosynthetic process; sphingomyelin biosynthetic process; sphingolipid biosynthetic process; sphingolipid metabolic process
Cellular component: cytoplasmic side of endoplasmic reticulum membrane; nucleoplasm; endoplasmic reticulum membrane; endoplasmic reticulum; membrane
Genetic constraint (gnomAD): Loss-of-function variants: 57 observed, 48.27 expected, observed/expected ratio (o/e) 1.18, 90% interval 0.95 to 1.47. The upper end of that interval is the gene's LOEUF score, 1.47, which puts it in group 6 of 6, group 1 being the genes least tolerant of losing a copy. Missense variants: 455 observed, 404.71 expected, observed/expected ratio (o/e) 1.12, 90% interval 1.04 to 1.22. Synonymous variants: 194 observed, 175.48 expected, observed/expected ratio (o/e) 1.11, 90% interval 0.98 to 1.25.
Homologues: Orthologues: chimpanzee CERS4 (98% identical), macaque CERS4 (93% identical), rabbit CERS4 (77% identical), dog CERS4 (76% identical), pig CERS4 (75% identical), rat Cers4 (70% identical), mouse Cers4 (69% identical), guinea pig CERS4 (57% identical), tropical clawed frog cers4 (49% identical), zebrafish cers4a (45% identical), zebrafish cers4b (43% identical), Drosophila melanogaster schlank (39% identical), and 2 more. Paralogues in human: CERS2 (45% identical), CERS3 (42% identical), CERS5 (42% identical), CERS6 (40% identical), CERS1 (25% identical).
Diseases named in the same sentence as CERS4 in open-access papers:
CERS4 is named in the same sentence as 44 diseases in open-access papers, as found by Europe PMC text mining. Sharing a sentence is not in itself a finding about the gene and the disease. The quoted sentences say what the papers report.
breast carcinoma (6 papers, 2016 to 2023). "This analysis revealed that higher CERS4 mRNA expression levels were associated with poor overall survival in LumA breast cancer (TCGA-BRCA, P = 0.048; GSE96058, P = 0.0014)." (PMID 37885013, 2023). "In human breast cancer tissue, there is higher CerS4 mRNA expression compared with healthy breast tissue." (PMID 37760612, 2023). "CerS4 knockdown partially reversed drug resistance in MCF-7/ADR cells treated with doxorubicin, paclitaxel, or tamoxifen, implying a critical role for CerS4 in the acquisition of MDR in breast cancer." (PMID 37885013, 2023). "One study suggested opposing roles for long-chain and very-long-chain ceramides in breast cancer growth, and CerS4-overexpressing MCF-7 cells were reported to exhibit lower cell viability and decreased colony formation than control MCF-7 cells." (PMID 37885013, 2023). "Analysis of the public datasets revealed elevated CERS4 expression in breast cancer, especially in the most common breast cancer subtype, LumA." (PMID 37885013, 2023). "Long-term CerS4 overexpression promotes breast cancer progression and invasiveness by activating several cancer-related signaling pathways, such as Akt/mTOR, NF-κB, and β-catenin, and inducing EMT." (PMID 37885013, 2023). "Although increased CerS4 expression in breast cancer has been reported, the molecular mechanisms underlying CerS4 function and its roles in breast cancer development and progression remain incompletely understood." (PMID 37885013, 2023). "Moreover, breast cancer patients with higher mRNA expression of CerS4, along with CerS1 and CerS5, show a worse prognosis than those with low CerS expression levels." (PMID 37760612, 2023). "The present study introduced the possible oncogenic role of CerS4 in LumA breast cancer." (PMID 37885013, 2023). "Chronic CerS4 overexpression may exert oncogenic effects in breast cancer via alterations in signaling, EMT, and chemoresistance." (PMID 37885013, 2023). "Analyses of CerS4 expression profiles could help optimize treatment plans and avoid ineffective therapies in breast cancer patients." (PMID 37885013, 2023). "Chronic alteration of CerS4 expression could critically impact breast cancer progression, metastasis and chemoresistance, positioning CerS4 as a novel target candidate for breast cancer therapy." (PMID 37885013, 2023). "Subtype-specific AS events in different CERS genes such as CERS2 in Luminal B subtype and CERS4 in Basal subtype suggest a strong subtype-specific post-transcriptional regulation of CERS genes that may play a role in breast cancer pathogenesis (Data set 8, 9)." (PMID 33568634, 2021). "Therefore, CerS4 may represent an attractive target for anticancer therapy, especially in LumA breast cancer." (PMID 37885013, 2023). "Therefore, targeting CerS4 could serve as a novel therapeutic approach to inhibit tumor growth, enhance sensitivity to chemotherapy, and potentially prevent metastasis in LumA breast cancer patients." (PMID 37885013, 2023). "Therefore, long-term CerS4 overexpression in breast cancer may also play essential roles in cancer cell migration and metastasis." (PMID 37885013, 2023). "Furthermore, MCF-7 cells stably overexpressing CerS4 (MCF-7/CerS4) as a model for luminal subtype A (LumA) breast cancer were produced, and doxorubicin (also known as Adriamycin [AD])-resistant MCF-7/ADR cells were generated after prolonged treatment of MCF-7 cells with doxorubicin." (PMID 37885013, 2023). "In human breast cancer, the mRNA expression levels of CERS2, CERS4, and CERS6 and their respective products, C16-, C24-, and C24:1-ceramides, are increased." (PMID 37885013, 2023). "Interestingly, CerS4 knockdown restored these phenotypes in MCF-7/ADR cells, indicating that CerS4 governs the EMT process in breast cancer and that reducing CerS4 expression may contribute to the shift of mesenchymal-like cancer cells toward an epithelial state." (PMID 37885013, 2023).
breast carcinoma (continued). "Although CerS4 is known to be overexpressed in breast cancer, its role in breast cancer pathogenesis is not well established." (PMID 37885013, 2023). "This approach revealed that persistent CerS4 overexpression in MCF-7 cells accelerated cell proliferation and MDR acquisition, suggesting that CerS4 may represent a potential therapeutic target in LumA breast cancer." (PMID 37885013, 2023).
colon cancer (4 papers, 2021 to 2024). "Instead, the Human Protein Atlas data show that reduced CerS4 expression in late-stage colon tumours is associated with a worse outcome in these patients." (PMID 38635059, 2024). "In contrast, CerS4 deficiency in epithelial cells resulted in smaller colon tumors and seemed to be beneficial." (PMID 35163788, 2022). "Additionally, overexpression of CerS4 in human colon cancer cells was associated with growth inhibition." (PMID 35163788, 2022). "CerS4 is also downregulated by cancer therapeutics such as anastrozole and 5-fluoruracil in colon cancer cells." (PMID 38635059, 2024). "Which of these factors are involved in the downregulation of CerS4 in colon cancer tissue needs to be investigated in future experiments." (PMID 38635059, 2024). "Overexpression of CerS2 and co-expression with CerS6 or CerS4 in colon cancer cells have been shown to promote proliferation, whereas overexpression of CerS4 and CerS6 had rather anti-proliferative effects." (PMID 38635059, 2024). "Different studies showed that in human colon tumor tissue, expression of CerS4 and the corresponding long-chain ceramides (Cer d18:1/18.0 and Cer d18:1/20:0) decreased." (PMID 35163788, 2022). "A closer look at the severity of the tumor growth revealed that in Vil/Cre mice, colon tumor development was limited to hyperplasia, while WT, CerS4 KO, and CerS4 LCK/Cre mice also showed dysplasia and neoplasia." (PMID 35163788, 2022). "CerS4 WT mice responded to DSS by the loss of body weight and symptoms of colitis such as diarrhea, bloody stool, and colon tumors 6 weeks after the last DSS cycle." (PMID 35163788, 2022). "Cell stress induces the cleavage of Myc, generating Myc-nick suggesting that cell stress may be a mechanism leading to the downregulation of CerS4 in colon cancer cells." (PMID 38635059, 2024). "Interestingly, CerS4 LCK/Cre mice developed significantly more colon tumors than CerS4 WT, CerS4 KO, and CerS4 Vil/Cre mice." (PMID 35163788, 2022). "To investigate the impact of CerS4 on tumour development and early carcinogenesis, we applied the AOM/DSS colon cancer model to CerS4 ko mice." (PMID 38635059, 2024). "It has been reported that overexpression of CERS4 and CERS6 in colon cancer cells induced the production of short-chain ceramides (C16: 0, C18: 0 and C20: 0 ceramides), weakened cell proliferation and promoted apoptosis." (PMID 37758931, 2023). "In contrast, CerS4 LCK/Cre mice frequently suffered from pancolitis and developed more colon tumors." (PMID 35163788, 2022). "Histological analysis of colon tumors by multiepitope ligand cartography (MELC) exhibited a high abundance of immune cells in colon tissue of AOM/DSS-treated WT and CerS4 LCK-Cre mice." (PMID 35163788, 2022). "Overexpression of CERS4 and CERS6 in breast and colon cancer cells, leading to an increase in short (C16:0) and long-chain ceramides (C18:0 and C20:0), inhibited cell proliferation and increased apoptosis." (PMID 33568634, 2021).
liver cancer (4 papers, 2021 to 2023). An epithelial or non-epithelial malignant neoplasm that arises from the liver. "In human liver cancer tissue, CerS4 is upregulated at the mRNA- and protein level and promotes liver cancer cell proliferation associated with NF-κB signaling." (PMID 37760612, 2023). "High expression of CERS4 was observed in liver cancer tissues, and it has been reported that the nuclear factor (NF)-κB signaling pathway was affected after knockdown of CERS4 in liver cancer cells." (PMID 37758931, 2023).
colitis (2 papers, 2022 to 2025). Inflammation of the colon. "CerS4 deficiency in T cells impairs T cell proliferation, and immune resolution, and enhances tumor progression in models of colitis and cancer, respectively." (PMID 40597360, 2025). "CerS4 plays a critical role in T cell function and immune responses in colitis and colitis-associated cancer." (PMID 40597360, 2025). "As CerS4 KO mice were more susceptible to acute DSS-induced colitis, we analyzed the immune cell status in the blood, spleen, and colon of these mice by flow cytometry." (PMID 35163788, 2022). "We showed a tissue-specific impact of CerS4 deficiency in DSS-induced colitis and AOM/DSS-induced CAC." (PMID 35163788, 2022). "To better understand the role of sphingolipids in the multifactorial process of inflammatory bowel disease (IBD), we elucidated the role of CerS4 in colitis and colitis-associated cancer (CAC)." (PMID 35163788, 2022). "Summing up, the higher susceptibility of CerS4 KO mice to DSS-induced colitis could be confirmed by increased infiltration of neutrophils and macrophages into the colon tissue of these mice in comparison with that in WT or CerS4 LCK/Cre mice." (PMID 35163788, 2022). "To investigate whether the susceptibility of CerS4 KO mice to DSS-induced colitis was related to a colon barrier dysfunction, we detected the expression of tight-junction proteins occludin and zonula occludens-1 (ZO-1) in the colon tissue of CerS4 WT and CerS4 KO mice." (PMID 35163788, 2022). "We already showed that CerS4 was significantly downregulated in white blood cells from human colitis patients in comparison with those from control patients." (PMID 35163788, 2022). "In conclusion, CerS4 KO and CerS4 LCK/Cre mice were more susceptible to AOM/DSS-induced colitis and CAC than WT mice, whereas CerS4 Vil/Cre mice developed smaller and only preneoplastic tumors in comparison with all other groups." (PMID 35163788, 2022). "To investigate the influence of CerS4 in colitis and CAC, we analyzed CerS4-deficient mice in a dextran sodium sulfate (DSS) and azoxymethane (AOM)/DSS model." (PMID 35163788, 2022). "For this, we utilized the azoxymethane/dextran sodium sulphate (AOM/DSS)-induced colitis model in global CerS4 knockout (CerS4 KO), intestinal epithelial (CerS4 Vil/Cre), or T-cell restricted knockout (CerS4 LCK/Cre) mice." (PMID 35163788, 2022). "CerS4 KO and CerS4 LCK/Cre but not CerS4 Vil/Cre mice were more susceptible to the DSS-induced colitis and AOM/DSS-induced CAC." (PMID 35163788, 2022). "However, in the acute inflammation model, the CerS4 KO mice and CerS4 LCK/Cre mice were most susceptible to colitis." (PMID 35163788, 2022). "Overall, our data showed that CerS4 knockdown plays an important role in colitis and CAC." (PMID 35163788, 2022). "Because DSS treatment also causes changes in other sphingolipids, the extent to which CerS4 generated-sphingolipids were responsible for the higher susceptibility of CerS4 KO mice to DSS-induced colitis could not be clearly stated." (PMID 35163788, 2022).
colorectal cancer (2 papers, 2023 to 2024). A primary or metastatic malignant neoplasm that affects the colon or rectum. "The first is that the Wnt pathway signal is involved in the regulation of CERS4 or the Wnt pathway may be involved in the KRAS mutation in colorectal cancer." (PMID 37758931, 2023). "There are many possible mechanisms by which CerS4 can be downregulated in colorectal cancer; how this can influence tumour development is summarized in the next chapter." (PMID 38635059, 2024). "We performed ROC analyses to define the optimal cut-off value for CERS4 expression in colorectal cancer tissue." (PMID 37758931, 2023). "Whether RNA editing of CerS4 is also relevant in colorectal cancer remains to be shown, but RNA editing is also increased in colorectal cancer." (PMID 38635059, 2024). "In the present study, expression of CERS4 was reduced in KRAS mutant colorectal cancer." (PMID 37758931, 2023). "Thus, even in KRAS mutant colorectal cancer, CERS4 expression may be reduced due to the influence of the NF-kB pathway." (PMID 37758931, 2023).
heart failure (2 papers, 2023). Inability of the heart to pump blood at an adequate rate to meet tissue metabolic requirements. "Studies have shown that CerS4 is expressed in the heart, has a high affinity for C18 and C20 acyl-CoA, and contributes to heart failure." (PMID 37456812, 2023). "Additionally, CERS4 can generate C20 and C22 ceramides, which have a protective function in the development of heart failure." (PMID 37298446, 2023).
lung adenocarcinoma (2 papers, 2016 to 2026). A carcinoma that arises from the lung and is characterized by the presence of malignant glandular epithelial cells. "In vitro, within lung adenocarcinoma cell lines, B4GALNT1 knockdown and CERS4 overexpression suppressed cell proliferation, migration, and epithelial-to-mesenchymal transition, supporting their roles in lung adenocarcinoma progression." (PMID 41666167, 2026). "Furthermore, the siRNA silencing of CerS6 robustly protected A549 lung adenocarcinoma cells from MTX toxicity, while the silencing of another ceramide synthase, CerS4, which was also responsive to folate stress in our previous study, did not interfere with the MTX effect." (PMID 26783755, 2016).
Obesity (2 papers, 2016 to 2023). Accumulation of substantial excess body fat. "Subsequently, abundant intestinal MYC targets ceramide synthase 4 (Cers4) to stimulate ceramide synthesis and simultaneously decrease glucagon-like peptide 1 (GLP-1) secretion, facilitating obesity." (PMID 37273529, 2023).
Chronic colitis (1 paper, 2022). A chronic inflammatory disease of the large intestine (colon, cecum and rectum). "After analyzing the outcome of the mice in the chronic colitis model, we were interested to understand the inflammatory response in the colon tissue and investigated CerS4 WT, KO, and LCK/Cre in an acute DSS model." (PMID 35163788, 2022).
COVID-19 (1 paper, 2023). A disease caused by infection with severe acute respiratory syndrome coronavirus 2. "Notably, in severe forms of COVID-19, ceramide synthases (CERS2, CERS4, and CERT1) responsible for the synthesis of Cer from Sph were upregulated." (PMID 37566018, 2023). "Furthermore, the expression levels of other enzymes associated with this pathway, such as ceramide synthase 2 (CERS2) and ceramide synthase 4 (CERS4), as well as the ceramide transfer protein (CERT1), were increased in severe COVID-19 patients." (PMID 37566018, 2023).
dermatitis (1 paper, 2019). An inflammatory process affecting the skin. "In IMQ-induced dermatitis, the expression of CerS1, CerS4, and CerS5 had a tendency to decrease, whereas the expression of CerS3 increased by 4.6-fold." (PMID 30838224, 2019). "In FAg-induced dermatitis, the expression of CerS1, CerS4, and CerS5 decreased, whereas the expression of CerS2 and CerS3 mildly increased with statistical significance." (PMID 30838224, 2019).
eczema (1 paper, 2025). "We had previously reported that deletion of CerS4 led to an eczema-like phenotype, but the molecular and cellular mechanisms were unclear." (PMID 39879198, 2025). "CerS4 deletion in mice showed macroscopic and histological characteristics of an AD-like eczema." (PMID 39879198, 2025).
glioma (1 paper, 2017). A benign or malignant brain and spinal cord tumor that arises from glial cells (astrocytes, oligodendrocytes, ependymal cells). "Interestingly, combined with the overexpression of CERS1 in glioma cells, the mRNA level of CERS4 was also increased." (PMID 29262618, 2017).
head and neck squamous cell carcinoma (1 paper, 2021). A squamous cell carcinoma that arises from any of the following anatomic sites: lip and oral cavity, nasal cavity, paranasal sinuses, pharynx, larynx, and salivary glands. "CERS4 expression was down-regulated in metastatic (late stage) head and neck squamous cell carcinoma (HNSCC), renal cell carcinoma, and melanoma, indicating that activation of CerS4/ceramide-Smad7 could target and inhibit tumor cell migration and invasion." (PMID 33996533, 2021).
influenza (1 paper, 2025). An acute viral infection of the respiratory tract, occurring in isolated cases, in epidemics, or in pandemics; it is caused by serologically different strains of viruses (influenzaviruses) designated A, B, and C, has a 3-day incubation period, and usually lasts for 3 to 10 days. "Collectively, these findings reveal a new function of CerS4 that restricts influenza virus infection and provides valuable insights into influenza-host defense interactions." (PMID 41217173, 2025). "However, influenza virus induces a decrease of CerS4 at the protein level upon infection, suggesting the presence of a complex interplay between host CerS4 and influenza." (PMID 41217173, 2025). "Thus, probing the mode of action by which influenza virus induces degradation of CerS4 may help identify host pro-influenza proteins and facilitate the design of host-directed antiviral therapeutics against influenza." (PMID 41217173, 2025).
lactose intolerance (1 paper, 2018). "We evaluated associations of C17:0 and C15:0 with SNPs in the LCT, and C23:0 with SNPs in CERS4, and SPTLC3 genes, providing new insights on potential influence of adult-onset lactose intolerance and sphingolipid synthesis on circulating levels of C17:0 and C23:0 respectively." (PMID 29738550, 2018).